NME2 (NME/NM23 nucleoside diphosphate kinase 2)
Diseases named in the same sentence as NME2 in open-access papers (continued):
Sharing a sentence is not in itself a finding about the gene and the disease.
cancer (47 papers, 2006 to 2025). A tumor composed of atypical neoplastic, often pleomorphic cells that invade other tissues. "We suggest that EV-derived NME1 and NME2 cause decreased lipid production in fibroblasts, thereby inhibiting lipid supply of cancer cells provided by fibroblasts at this early stage of metabolic symbiosis." (PMID 36010906, 2022). "Our knowledge about the involvement of NME2 in different cancer types is rather limited: it has been implicated in oral squamous, breast, prostate, lung and ovarian cancers." (PMID 36010906, 2022). "Because altered NME2 has been detected in multiple cancer tissues (14, 17, –, 19), it is of interest to understand the mechanisms underlying low NME2 and enhanced hTERT expression/activation." (PMID 28717007, 2017). "This suggested that regulatory potential of NME2 is closely linked to progression into advanced cancers with metastatic proclivity." (PMID 25249619, 2014). "Several studies have implicated NME2 as a regulator of genes implicated in cancer progression such as c-MYC, PDGF-A, ITGAM and telomerase." (PMID 25249619, 2014). "In this context, the analysis of the transcription factor of NME2 gene suggested that DNA repair might be associated with the biogenesis of cancer stem cells." (PMID 36153608, 2022). "The PAAD ColX module is enriched for targets of the transcription factor NME2, which regulates cancer cell proliferation in a variety of contexts through activation of MYC." (PMID 39939916, 2025). "Aberrant PIWIL2 expression has been implicated in promoting proliferation in HCC and other cancers, with its tumorigenic functions mediated through interactions with HDAC3, NME2, β-catenin (CTNNB1), and others via the PIWI and MID domains." (PMID 41422314, 2025). "NME2 promotes proliferation and tumor growth in different cancers, such as HCC and lung and cervical cancers." (PMID 39063217, 2024). "Whereas the role of NME1 in cancer has been extensively studied, the role of NME2 is less well understood." (PMID 39063217, 2024). "An increasing number of studies implicate NME1 and NME2 in cancer, but depending on the cancer context, they can either be protumorigenic or tumor suppressive." (PMID 39063217, 2024). "Aside from the correlations with CYP24A1, nucleoside diphosphate kinase 2, NME2, is a metastasis suppressor in many types of cancer." (PMID 35642922, 2022). "In this study, we focused on the first identified metastasis suppressor NME1, and on its close homolog NME2, and investigated their function in EVs in the interplay between cancer and stromal cells." (PMID 36010906, 2022). "Among the genes, SPAG9, NME1, and NME2 are involved in regulating the proliferation of cancer cells." (PMID 30901931, 2019). "Nucleoside diphosphate alkylase 2 (NME2), which is an active cancer suppressor, was highly expressed in Spalax tissues." (PMID 30621584, 2019). "Together with findings reported here, this indicates a possible dual role of NME2 in control of telomerase in cancer cells." (PMID 28717007, 2017). "These in vitro experiments are designed to understand the invasiveness of cancer cells that express different levels of NME2." (PMID 25700270, 2015). "The study is necessary because NME2 was initially identified as the first metastasis suppressor gene, but its ability to block cancer local invasion and remote metastasis appears to be cell type specific among cancers that have so far been studied." (PMID 25700270, 2015). "Exact reasons for the discrepancy remains to be further investigated, but these data suggest cell type-specific effects of the NME2 gene on the pathogenesis of cancers." (PMID 25700270, 2015). "Among the members of this gene family, NME1 and NME2 have been extensively studied for their cancer-suppressing activities." (PMID 25700270, 2015). "Collectively, these results demonstrate that NME2-mediated regulation of vinculin favors a signaling pathway that contributes to invasiveness and metastasis of cancer cells." (PMID 25249619, 2014).
cancer (continued). "As we used human cancer cells that are metastatic, and expression of the TF NME2 decreased their metastatic potential, these findings also help in understanding how TF binding-induced nucleosome level changes influence the transcriptome during metastasis." (PMID 25081206, 2014). "Thus, while the precise mechanism of NME2 association with DNA may be currently unknown, it is clear from the results obtained in this study that NME2 can influence the gene regulatory program of cancer cells." (PMID 25249619, 2014). "This contradictory phenomenon highlights the dual role of NME2, suggesting that its influence on tumorigenesis may vary across cancer types." (PMID 41476960, 2025). "Most of the published studies have focused on the role of NME1 and NME2 in cancer independently of their histidine kinase function, which might help explain some of the contradictory results observed thus far." (PMID 39063217, 2024). "This raises the question of what exactly is the function of NME2 in cancer." (PMID 33918324, 2021). "Moreover, they establish the metastasis-suppressor function of Nme2 for the first time in an in vivo model of spontaneous cancer of any kind, thereby suggesting a similar function for the human NME2 gene." (PMID 33024267, 2021). "As reported, NME2 can suppress the metastasis and invasion of cancer cells." (PMID 34628473, 2021). "NME2 have been extensively studied in the past for their cancer-suppressing activities." (PMID 30621584, 2019). "Another prognostic marker of cancer development, nucleoside diphosphate alkylase 2 (NME2), was differentially expressed in our study’s mouse samples (low expression level) and in Spalax samples (high expression level), including samples derived from the UIS of cancer-sensitive Spalax." (PMID 30621584, 2019). "A multifunctional protein which may be related to energy insufficiency in cancer cachexia is Nme2, which is involved in the synthesis of nucleoside triphosphates other than ATP, and is downregulated in both gastrocnemius and cardiac muscles." (PMID 29774118, 2018). "Together, these data suggested NME2-mediated transcriptional repression of hTERT in cancer cells." (PMID 28717007, 2017). "A system biology approach to examine these specific pathways instead of individual molecules may be required to dissect roles of the NME2 gene and its product in different types of cancers." (PMID 25700270, 2015). "However, it is inconsistent with reports that NME2 promotes or reduces the proliferation of other types of cancer cells." (PMID 25700270, 2015). "As primary lung tumors frequently metastasize to brain and bone, we checked whether gene expression program of NME2-depleted cancer cells compared to transcriptomes of brain and bone metastases." (PMID 25249619, 2014). "Furthermore, our findings for the first time underline the importance of these aspects of chromatin biology in suppression of cancer spread mediated by NME2." (PMID 25081206, 2014). "However, the role of histidine kinase activity of NME2 in cancer remains to be determined." (PMID 39063217, 2024). "Whether and how NME2 expression might be modulated during cancer progression remains unknown." (PMID 33918324, 2021). "As a transcription factor, NME2 acts on the oncogene c-MYC, which is involved in the development of cancer." (PMID 36836717, 2023). "This approach identified CREG1, NME2, and TSPYL5 as frequently altered across multiple cancers." (PMID 41476960, 2025). "CREG1, NME2, and TSPYL5 exhibited significant CNV across pan-cancer types." (PMID 41476960, 2025). "The other common MS genes, including CD28, KISS1, NME2, BRMS1, shared in over 10 cancer types." (PMID 26486520, 2015).
tumor (43 papers, 1995 to 2025). "The overexpression of NME2 was significantly associated with not only clinical parameters related to tumor progression, invasion, and metastasis but also resistance to 5-FU treatment." (PMID 34208938, 2021). "Proteins, HLAB, ADAMTS2, LTBP3, JAG2 and NME2 were significantly associated with tumor progression, vascular invasion and distant liver metastasis." (PMID 30679934, 2019). "Six of the 10 (60%) proteins examined using TMA immunohistochemistry, HLAB, protein 14-3-3β, LTBP3, ADAMTS2, JAG2 and NME2, were significantly associated with clinical parameters which have shown to relate with tumor progression, invasion and metastasis." (PMID 30679934, 2019). "Expression of HLAB, protein 14-3-3β, LTBP3, ADAMTS2, JAG2 and NME2 on tumour cells was significantly associated with clinical parameters related to tumour progression, invasion and metastasis." (PMID 30679934, 2019). "Our study showed that the expression of NME2 in tumour cells significantly associated with histological grade of tumour and vascular invasion." (PMID 30679934, 2019). "Deficiency of either PIWIL2 or NME2 protein impairs the c-Myc expression, leading to defects in cell cycle progress and proliferation in tumor cells." (PMID 25193865, 2014). "Given its involvement in nucleotide metabolism, NME2 overexpression could potentially fuel both anabolic processes and the associated metabolic pathways, thereby simultaneously supporting tumor proliferation and fostering an immunosuppressive niche." (PMID 41476960, 2025). "Expression of HLAB, ADAMTS2, LTBP3, JAG2 and NME2 on tumour cells, was associated with tumour progression and invasion, metastasis and CRC specific survival may serve as potential biomarkers to stratify CRC patients into low and high risk of tumour metastasis." (PMID 30679934, 2019). "The higher rate of face tumours in HPN2 versus HP or HPN1 mice suggests Nme2 deficiency imparts a more external and UV-exposed location of melanocytes in face skin, or that Nme2 might play a more dominant role than Nme1 in the repair of UV-induced DNA damage in those melanocytes." (PMID 33024267, 2021). "In Hela or HepG2 cells, Piwi-like RNA-mediated gene silencing 2 (PIWIL2) can upregulate c-Myc via promoting the binding of NME2 to the c-Myc promoter, inducing tumor cell proliferation." (PMID 39063217, 2024). "Enzalutamide alone had a minimal effect under the tested dosing conditions, while NME2 knockdown (with Doxycycline in drinking water) re-sensitized tumors to Enzalutamide, with an average tumor growth inhibition of 62%." (PMID 38191557, 2024). "Accordingly, NME1 and NME2 are overexpressed early in the primary tumor and only NME1 expression is reduced or repressed at later stages in colorectal and hepatic tumors that have undergone metastasis." (PMID 37353690, 2023). "The results revealed that the tumor growth in the mice treated with NME2-shRNA was significantly suppressed compared with the control." (PMID 34628473, 2021). "NME1 and NME2 have been reported to be over-expressed in CRC tumor tissues compared with normal tissues in a significant proportion of the patients." (PMID 34113558, 2021). "Some size differences were also found with larger tumors obtained upon injection of NME2 KO cells, which correlated with higher percentage of PCNA-positive cells in NME2-KO tumor xenografts as compared to NT or NME1-KO tumors." (PMID 34012098, 2021). "The ability of NME1 or NME2 to influence tumor invasion was evaluated using the intraductal xenograft model involving the injection of human MCF10DCIS.com cells into the primary duct of mouse mammary glands." (PMID 34012098, 2021). "Whereas numerous studies support the conclusion that loss of NME1 expression correlates with metastasis and poor clinical prognosis in many types of human tumor, the role of its highly homologous isoform, NME2, in malignancy is only poorly documented." (PMID 33918324, 2021).
tumor (continued). "Whereas the involvement of NME1 in tumor invasion and metastasis has been widely addressed, its role and the role of NME2 in EMT has hardly been studied." (PMID 33918324, 2021). "The catalytic activity of NME2 is similar to that of NME1 (NME1: 748 U/mg and NME2: 609 U/mg; unpublished data) and this isoform has also been observed to be overexpressed during tumor proliferation." (PMID 33918324, 2021). "It would be interesting to determine NME2 protein levels in different subregions of the tumor, i.e., in the highly proliferative central area and at the invasive front." (PMID 33918324, 2021). "Through topology analysis, NME2, and NFBIKA were implicated as tumor suppressor TFs because of their absence in a tumor regulatory network and high connectivity in a non-tumor network." (PMID 33424926, 2020). "JAG2 expression on tumour cells was significantly associated with mucinous (p = 0.044) and LVI (p = 0.038) and NME2 were significantly correlated with histological grade and LVI at p = 0.032 and p = 0.048 respectively." (PMID 30679934, 2019). "Based on these findings, we propose a model of metastasis control in which reduced expression of NME2 in tumor cells perturbs focal adhesion signaling by enhancing expression of vinculin." (PMID 25249619, 2014). "Next patient tumor DNA and tissues were examined for expression of NME2 during progression from early to advanced stages, and lymph node metastases." (PMID 25249619, 2014). "Our current study reveals that PIWIL2 raises c-Myc expression by binding to NME2, and subsequently enhances tumor cell proliferation and F-actin filaments." (PMID 25193865, 2014). "Additional findings obtained here show that PIWIL2 is a new partner of NME2 in tumor cells, and the role of this interaction in c-Myc transcriptional regulation needs to be further elucidated." (PMID 25193865, 2014). "According to our data analysis, NME2’s tumor-promotive role in ccRCC may involve metabolic reprogramming, as high-SRSM tumors showed enhanced oxidative phosphorylation." (PMID 41476960, 2025). "To evaluate whether NME2 tumor expression has a direct role in promoting resistance to Enzalutamide in vivo, we sought to test the hypothesis that loss of NME2 in Enzalutamide-resistant C42B cells is sufficient to restore Enzalutamide sensitivity." (PMID 38191557, 2024). "Due to the dichotomous role of NME2 in metastasis, whether NME2 promotes or suppresses metastasis could be dependent on the specific cellular environment, genetic, and tumor microenvironment." (PMID 39063217, 2024). "We hypothesise that that NME1 and NME2 function as NDPKs at early stages of tumorigenesis, providing nucleoside triphosphates to sustain the high proliferation of tumor cells." (PMID 37353690, 2023). "The NME2 and NME4 genes encode proteins within the NDK (nucleoside diphosphate kinase) family and have multiple functions in cellular energetics, signaling, proliferation, differentiation, and tumor invasion." (PMID 35350385, 2022). "NME2 expression was significantly reduced in metastatic compared to non-metastatic tumour variants in some cohorts of patients with breast, lung and ovarian tumours." (PMID 36010906, 2022). "We also measured the protein levels of ADAM10 in tumor cells genetically modified for NME1 or NME2." (PMID 33918324, 2021). "Similarly, NME2 KO cells gave rise mostly to in situ tumors, with a very small subset of tumor foci (2–3%) having invasive features." (PMID 34012098, 2021). "The results showed that the tumor growth of the mice injected with NME2-knockout cells (NME2 KO) was significantly suppressed compared with that of the mice injected with wild-type NME2 cells (NME2 WT)." (PMID 34628473, 2021). "Finally, we investigated the consequences of the modulation of NME1/NME2 levels on the ability of tumor cells to proteolytically cleave the surrounding type I collagen fibers." (PMID 34012098, 2021). "Strong expression of NME2 in tumour cells indicated good CRC specific survival." (PMID 30679934, 2019).
tumor (continued). "The high level of expression of NME2 gene in the Spalax-sensitive samples found in our study may explain to a certain extent the significant delay of tumor development and the tumors’ benign nature in half the cases." (PMID 30621584, 2019). "To ascertain whether NME2 protein level after induction in A549 cells was still in the physiological range, we analyzed protein expression of NME2 in normal lung lysates and tumor lung, and compared with NME2-induced A549 cells." (PMID 25081206, 2014). "Quantitative real-time (qRT) PCR for NME2 showed significantly reduced transcript level in advanced stage tumor samples (n = 44, ∼1.7-fold depletion; equivalent to 41% decrease, P < 0.003) confirming the trend observed in tumor transcriptome meta-analyses." (PMID 25249619, 2014). "To disrupt these interactions, we designed novel decoy peptides that potentially competes with both HDAC3 and NME2, effectively inhibiting PIWIL2-driven tumor activity in Huh7, HepG2, SNU449, and SNU398 HCC cell lines." (PMID 41422314, 2025). "NME/NM23 nucleoside diphosphate kinase 2 (NME2), a ubiquitous enzyme isoform, transforms nucleoside diphosphates into triphosphates, and well known for its homologue NME1 that is a tumor metastatic suppressor." (PMID 25193865, 2014). "Similarly, genes such as NME2 and NPM1, which play a role in cell cycle and tumor suppression, were consistently downregulated in both datasets." (PMID 40692702, 2024). "For two of the TSGs (Chuk and Nme2) that were identified using the GUST-mouse model but not using the 20/20 rule, substantial existing experimental evidence supported their tumor-suppressing activities." (PMID 37958330, 2023). "Nevertheless, growth rates of primary tumours in HPN2 mice were not correlated with lung metastasis or lymph-node enlargement scores, indicating the impact of Nme2 ablation on metastasis was independent of its effect on primary tumour growth." (PMID 33024267, 2021). "NME2 and NFKBIA represent putative tumor suppressor factors for future studies." (PMID 33424926, 2020). "Moreover, a low level of histidine phosphatase LHPP was correlated with high PRAME expression in PRAME-positive UM tumor cells, but opposite phenomenon as high level of histidine kinase (NME1 and NME2), which indicates that low LHPP expression forebodes a risk of easier metastasis." (PMID 40988976, 2025). "NME2 has been reported to be an inhibitor of cell motility and invasion, suggesting that it might have a similar function to NME1 during tumor progression as an inhibitor of metastasis." (PMID 37353690, 2023). "Indeed, loss of NME2, unlike NME1, does not impair the invasive capacity of tumor cells or the transition from in situ to invasive breast carcinoma in the intraductal xenograft model." (PMID 37353690, 2023). "Besides, when NME2 expression vector was co-transfected with shPIWIL2, the specific band indicating NME2/PIWIL2/G4-motif complex remained undetected, suggesting that interaction between NME2 and G4-motif complex is PIWIL2-dependent in tumor cells." (PMID 25193865, 2014). "In contrast to these earlier studies, however, our work rather suggests that NME2 is not a suppressor of EMT and tumor invasion." (PMID 37353690, 2023). "Suppression of NME1, but not that of NME2, accelerated the invasive switch of MCF10DCIS.com tumor xenografts in the intraductal injection model." (PMID 34012098, 2021).
adenocarcinoma (2 papers, 2014 to 2024). A common cancer characterized by the presence of malignant glandular cells. "Following adenocarcinoma identification, we evaluated activity levels of the MYC pathway and NME2 TR program in both neoadjuvant and adjuvant samples." (PMID 38191557, 2024).